ADA (adenosine deaminase)
Diseases named in the same sentence as ADA in open-access papers (continued):
Sharing a sentence is not in itself a finding about the gene and the disease.
Lymphadenopathy (1 paper, 2022). Enlargement (swelling) of a lymph node. "We also analyzed the correlation of ADA activity with fever, skin rash, Lymphadenopathy and other clinical manifestations." (PMID 35090387, 2022).
male infertility (1 paper, 2025). The inability of the male to effect fertilization of an ovum after a specified period of unprotected intercourse. "Elevated ADA abundance has been detected in the serum of infertile men, indicating that ADA is associated with male infertility, and increased ADA level may indirectly reflect reduced sperm quality." (PMID 41463814, 2025).
malignant peripheral nerve sheath tumor (1 paper, 2022). Malignant peripheral nerve sheath tumor (MPNST) is a rare and often aggressive soft tissue sarcoma occurring in a wide range of anatomical sites. "Indeed, prior studies found that inhibiting ADA can sensitize trypanosomiasis models to cordycepin treatment, and this was also investigated in a limited number of malignant peripheral nerve sheath tumor (MPNST) and leukemic lines." (PMID 35804893, 2022).
malignant tumors of the eye (1 paper, 2022). "Combination therapy with cordycepin and ADA inhibitors was effective in treating a range of malignant tumors of the eye, brain, and pancreas." (PMID 35804893, 2022).
memory impairment (1 paper, 2025). "However, in the groups supplemented with 10% and 20% cashew nuts, there was a statistically significant reduction (p < 0.05), with the important note that increased ADA is associated with memory impairment." (PMID 40298810, 2025).
metastatic tumor (1 paper, 2012). "Moreover, primary MB tumor cells, Daoy and ONS76 express the ecto-5′NT/CD73 while D283 representative of a metastatic tumor, revealed poor expression of this enzyme, while the ecto-adenosine deaminase showed higher expression in D283 compared to Daoy and ONS76 cells." (PMID 23094051, 2012).
migraine (1 paper, 2015). "The aim of this study was to investigate single nucleotide polymorphisms (SNPs) in the adenosine deaminase, RNA-specific, B1 (ADARB1) and adenosine deaminase, RNA specific, B2 (ADARB2) genes in an Australian case–control Caucasian population for association with migraine." (PMID 25916332, 2015).
miliary tuberculosis (1 paper, 2017). I would say the hematogenous widespread dissemination of tuberculosis in the body. "In our study, elevated median levels of ADA, ESR and CRP were observed in patients with miliary tuberculosis alone, but only an elevated median level of ESR was observed in those complicated with CNS tuberculosis." (PMID 28531173, 2017). "Many studies have shown decreased levels of HGB and ALB, elevated levels of adenosine deaminase (ADA) and CRP, and increased ESR in miliary tuberculosis patients." (PMID 28531173, 2017).
nephrotoxicity (1 paper, 2022). Toxicity that causes injury to the kidney or damages its function. "TO triggered protective activity in Cd-induced nephrotoxicity in rats and prevented modifications in renal function biomarkers (creatinine, urea, BUN), inflammatory cytokines (IL-6 and TNF-α), and renal adenosine deaminase (ADA) activity." (PMID 36014301, 2022).
neuromyelitis optica (1 paper, 2025). A rare inflammatory disease of the central nervous system characterized mainly by attacks of uni- or bilateral optic neuritis (ON) and acute myelitis. "CSF analysis of Cysticercosis, Neuromyelitis Optica (NMO)/Aquaporin-4-IgG Fluorescence-Activated Cell Sorting (FACS), and adenosine deaminase all returned negative." (PMID 40171340, 2025).
oral diseases (1 paper, 2019). "Adenosine deaminase (ADA) is involved in various processes related with the immune system, it is considered a biomarker of inflammation and it has been found to change in saliva in oral diseases." (PMID 30799975, 2019).
oral squamous cell carcinoma (1 paper, 2022). "ADA level in serum may be a biomarker for diagnosis and prognosis of oral squamous cell carcinoma." (PMID 35433762, 2022).
ovarian neoplasm (1 paper, 2017). A benign, borderline, or malignant neoplasm involving the ovary. "Among the 7 mRNAs, ADA (Adenosine Deaminase) is a well-studied gene in ovarian neoplasms." (PMID 29270229, 2017).
paroxysmal AF (1 paper, 2022). "Moreover, adenosine deaminase (ADA) activity is decreased in patients with paroxysmal AF contrary to patients with isolated dilated left atrium without AF." (PMID 36428533, 2022).
Plasmodium vivax malaria (1 paper, 2006). Malaria resulting from infection by Plasmodium vivax. "There has been no previous investigation of serum ADA levels in P. falciparum malaria but serum ADA levels were found to be elevated to more than twice the level of controls in a previous study on patients with Plasmodium vivax malaria." (PMID 16764711, 2006).
pneumococcal infection (1 paper, 2015). Infections with bacteria of the species streptococcus pneumoniae. "Previous studies indicate that administration of the ADA inhibitor EHNA-hydrochloride and the CD73 inhibitor α,β methylene ADP to mice results in the predicted effects on adenosine concentration, but we did not directly measure changes in EAD levels during pneumococcal infection." (PMID 26313746, 2015).
polyarticular JIA (1 paper, 2021). "ADA-positive patients concerned different JIA-subtypes, no subtype was outstanding (n = 1 artritis psoriatica, n = 1 oligo-extended JIA, n = 3 RF+ polyarticular JIA, n = 3 RF- polyarticular JIA)." (PMID 33926495, 2021).
Priapism (1 paper, 2020). A painful and harmful medical condition in which the erect penis doesn't return to its flaccid state, despite the absence of both physical and psychological stimulation, within four hours. "In the literature, excess of adenosine in murine penile erectile tissues has been described associated with priapism: This study highlights how adenosine deaminase plays a biological role in different tissues and systems." (PMID 32307643, 2020).
proctitis (1 paper, 2025). An inflammatory process affecting the anus. "Regarding positive signals, the strongest ones were adenosine deaminase decreased (n = 4), large intestine erosion (n = 7), ileocaecal resection (n = 4), ileal ulcer (n = 8), and proctitis ulcerative (n = 3)." (PMID 41306780, 2025).
psychosis (1 paper, 2025). "Binary logistic regression analysis showed that serum ADA levels were 62.2% accurate in predicting psychosis risk, with a sensitivity of 82%." (PMID 40439810, 2025). "Our primary objective is to investigate the sensitivity and specificity of peripheral adenosine deaminase enzyme levels regarding susceptibility to psychosis." (PMID 40439810, 2025). "Importantly, to our knowledge, this study is the first to assess the utility of serum ADA levels in establishing psychosis risk, highlighting its potential significance in early intervention strategies." (PMID 40439810, 2025). "However, no publications have investigated ADA level measurement as useful for the prediction of psychosis risk." (PMID 40439810, 2025).
pulmonary sarcoidosis (1 paper, 2021). Sarcoidosis affecting the lung parenchyma. "Although some markers, such as serum angiotensin-converting enzyme, adenosine deaminase, CXCLs, YKL-40, and neopterin, indicate the activity of pulmonary sarcoidosis, specific markers that reflect the severity and prognosis of pulmonary sarcoidosis are still lacking." (PMID 35186971, 2021).
Pythiosis (1 paper, 2015). A granulomatous disease caused by the aquatic organism PYTHIUM insidiosum and occurring primarily in horses, cattle, dogs, cats, fishes, and rarely in humans. "The tissue activity of the proinflammatory enzyme adenosine deaminase and the histological pattern observed in pythiosis lesions of rabbits treated with deferasirox were similar to the ones in animals treated with immunotherapy." (PMID 25738758, 2015). "The activity of the immunomodulatory enzyme ADA and the cellular pattern in rabbit pythiosis lesions that were treated with deferasirox were similar to those treated with immunotherapy." (PMID 25738758, 2015). "In support to our findings, a decreased lymphocyte ecto-ADA activity has been previously reported in rabbits with pythiosis, an effect that was also reversed by immunotherapy." (PMID 25738758, 2015). "The impact of deferasirox in modulating the immune response was compared to immunotherapy by histopathological analysis and by measuring ADA activity in the lesions of rabbits with experimental pythiosis." (PMID 25738758, 2015). "Therefore, the impact of deferasirox in modulating the immune response was compared to immunotherapy by histopathological analysis and by measuring ADA activity in the lesions of rabbits with experimental pythiosis." (PMID 25738758, 2015).
Rectal prolapse (1 paper, 2020). Protrusion of the rectal mucous membrane through the anus. "Modifications in the levels of acute phase proteins or ADA were only recorded in animals with lameness and rectal prolapse and those with fatigue respectively." (PMID 32000745, 2020). "Some markers were more pronounced in a specific condition, such as Cu or Cd in healthy animals or CRP and Hp in rectal prolapse or lameness, while other markers were lacking, such us ADA or CRP in healthy animals or Cu in all pathological conditions." (PMID 32000745, 2020).
red cell aplasia (1 paper, 2025). "The enrichment results in C5 sets revealed that GSK-3β may be related to abnormal erythrocyte adenosine deaminase activity, pure red cell aplasia, and erythroid hypoplasia." (PMID 41321870, 2025).
renal carcinoma (1 paper, 2024). A carcinoma arising from the epithelium of the renal parenchyma or the renal pelvis. "The upregulated ADA activity is associated with the staging of gastric, bladder, breast, colorectal, and renal cancers." (PMID 39445019, 2024).
respiratory failure (1 paper, 2019). The significant impairment of gas exchange within the lungs resulting in hypoxia, hypercarbia, or both, to the extent that organ tissue perfusion is severely compromised. "Hearing onset in mice occurs at 11–13 days pp and ADA–/– mice suffer respiratory failure and death by 19–21 days pp, therefore ABR testing was performed at 17 days pp." (PMID 30918508, 2019).
scrub typhus (1 paper, 2013). Scrub typhus is a rare dust mite-borne infectious disease caused by the Orientia tsutsugamushi bacterium and characterized clinically by an eruptive fever which is potentially serious. "Since India is endemic for both TB and scrub typhus, awareness of simple-to-treat scrub typhus with access to specific tests like scrub IgM and CSF ADA may go a long way in avoiding unwarranted treatment in patients." (PMID 23799119, 2013).
spina bifida (1 paper, 2012). A congenital neural tube defect in which vertebrae are not fully formed. "Interestingly, ADA activity was significantly elevated in a study of 68 pregnant women carrying a fetus with a central nervous system malformation; of these women, 17 had a spina bifida pregnancy." (PMID 22856873, 2012).
steatosis (1 paper, 2023). Increased lipid within the cytoplasm of cells. "In conclusion, we propose that steatosis is the most common finding noted in our ADA-SCID cohort." (PMID 37208598, 2023).
subacute sclerosing panencephalitis (1 paper, 2012). A chronic progressive encephalitis that develops a few years after measles infection and presents with a demyelination of the cerebral cortex. "A host double-stranded RNA-specific adenosine deaminase ADAR1 is induced by MeV infection, and U-to-C transition substitutions are introduced exclusively within the M gene, resulting in emergence of defective viruses, which cause subacute sclerosing panencephalitis (SSPE)." (PMID 23185501, 2012).
systemic sclerosis (1 paper, 2020). A chronic disorder, possibly autoimmune, marked by excessive production of collagen which results in hardening and thickening of body tissues. "Furthermore, PEGylated adenosine deaminase is currently employed as an enzyme replacement therapy for patients suffering adenosine deaminase severe combined immunodeficiency and has lately been shown to alleviate fibrosis and inflammation in a murine model of systemic sclerosis." (PMID 33519814, 2020).
T-cell acute lymphoblastic leukemia (1 paper, 2024). Acute lymphoblastic leukemia of T-cell origin. "However, we recently reported a single case of T-cell acute lymphoblastic leukemia related to GT in the analysis on long-term safety and efficacy of 43 ADA-SCID patients who received retroviral ex vivo HSPC GT18." (PMID 38688902, 2024).
T-cell lymphomas (1 paper, 2023). "Interestingly, patients with shown factors such as T-cell lymphoma, stages III-IV, “B” symptoms and ulcerative type were often accompanied by abnormal levels of LDH, ADA, HGB and ALB." (PMID 37397371, 2023).
temporal lobe epilepsy (1 paper, 2024). A localization-related (focal) form of epilepsy characterized by recurrent seizures that arise from foci within the temporal lobe, most commonly from its mesial aspect. "The overexpression of the adenosine kinase (ADK) and adenosine deaminase (ADA) genes was found to be associated with neuronal hyperexcitability and seizure activity in temporal lobe epilepsy." (PMID 38641945, 2024).
thymic benign tumors (1 paper, 2024). "There was a causal relationship between adenosine deaminase levels and thymic benign tumors, a risk factor (IWV, p = 0.042, OR = 2.082, 95% CI: 1.026–4.225)." (PMID 38828408, 2024).
thymus atrophy (1 paper, 2021). Acquired diminution of the size of the thymus associated with wasting as from death and reabsorbtion of cells, diminished cellular proliferation, decreased cellular volume, pressure, ischemia, malnutrition, reduced function or malfunction, or hormonal changes. "Therefore, we cannot exclude that the deleterious effect of the lack of ADA expression during development of HSPCs in Ada−/− mice may contribute to thymus atrophy by affecting the production of thymic seeding progenitor populations." (PMID 34853379, 2021).
toxoplasmosis (1 paper, 2021). A parasitic disease contracted by the ingestion or fetal transmission of toxoplasma gondii. "This increase in ADA activity has been described in the course of diseases that induce a cellular immune response, as for example in neosporosis and toxoplasmosis." (PMID 34551803, 2021).
triple-negative breast carcinoma (1 paper, 2025). An invasive breast carcinoma which is negative for expression of estrogen receptor (ER), progesterone receptor (PR), and human epidermal growth factor receptor 2 (HER2). "We first optimized cgRNA for CRISPR-Cas13d editing of adenosine deaminase acting on RNA type I (Adar1) transcript for the combination immunotherapy of triple negative breast cancer (TNBC)." (PMID 40777396, 2025).
uveal melanoma (1 paper, 2022). A melanoma derived from melanocytes of the uveal tract. "In this study, we found that ADA expression and/or activity varies in uveal melanoma and other types of cancer cells and that higher levels are associated with less potent therapeutic effects of cordycepin." (PMID 35804893, 2022). "The SynergyFinder program was used to choose a concentration of cordycepin and ADA inhibitors in uveal melanoma cells." (PMID 35804893, 2022). "Consistent with the results in uveal melanoma, the therapeutic effects of cordycepin varied depending on ADA in other types of cancer as well." (PMID 35804893, 2022). "Consistent with our in vitro results in uveal melanoma with reduced ADA expression, treatment with 20 mg/kg body weight (b.w.)of cordycepin significantly suppressed the tumor growth in 92.1 uveal melanoma xenografts with low ADA protein." (PMID 35804893, 2022). "Inhibition of ADA activity using siADA and small molecule ADA inhibitors greatly enhanced the anticancer effects of low cordycepin concentration (1–20 μM) in uveal melanoma cells, with a significant score in formal synergy testing." (PMID 35804893, 2022). "When taken together, these results indicate that the inhibition of ADA function enhances antitumor effects of cordycepin in uveal melanoma with both low ADA and high ADA expressed." (PMID 35804893, 2022). "A total of 92.1 uveal melanoma cells with low ADA expression showed a significant, dose-dependent decrease in colony formation after 80 μM and 160 μM cordycepin treatment." (PMID 35804893, 2022). "Second, we show that inhibition of ADA enhances cordycepin’s anticancer effects by blocking its conversion to 3′-deoxyinosine in uveal melanoma and several other tumors." (PMID 35804893, 2022). "Our examination of human uveal melanoma tissues showed that more than 90% of tumors had lower expression levels of ADA protein, suggesting that cordycepin treatment may be effective in a large proportion of cases." (PMID 35804893, 2022). "Previous work had shown that 3′-deoxyadenosine/cordycepin is converted to 3′-deoxyinosine by the ADA enzyme, and we hypothesized that different expression levels or activity of ADA might explain the heterogeneous response in uveal melanoma cells." (PMID 35804893, 2022). "When taken together, these results indicate that ADA expression or activity could be a predictive biomarker for cordycepin treatment of uveal melanoma." (PMID 35804893, 2022). "To determine if combination therapy could further sensitize uveal melanoma cells to cordycepin, we used pharmacologic inhibition of ADA." (PMID 35804893, 2022). "Cordycepin slows migration, growth, and clonogenicity of uveal melanoma and other aggressive malignancies with low ADA levels, but all tumors tested could be sensitized through co-treatment with ADA inhibitors." (PMID 35804893, 2022). "Finally, we examined ADA protein in primary human uveal melanoma specimens by immunohistochemical analysis of a tissue array, which confirmed heterogeneous expression levels in primary tumors." (PMID 35804893, 2022). "In addition, Combination treatment with 10 μM of cordycepin and 1 μM of an ADA inhibitor (EHNA or pentostatin) significantly inhibited migrated cells in all uveal melanoma cell lines." (PMID 35804893, 2022). "ADA protein was differentially expressed in our uveal melanoma cell lines." (PMID 35804893, 2022). "Therefore, we hypothesized that ADA expression or activity levels could modulate the anticancer effects of cordycepin in uveal melanoma cell lines." (PMID 35804893, 2022). "A total of 160 μM cordycepin treatment decreased mRNA expression of VEGF in ADA-low uveal melanoma, while it was not decreased in high ADA uveal melanoma cells." (PMID 35804893, 2022). "Cordycepin single treatment increased cleaved PARP protein expression in ADA low (92.1, MM28, Omm1) uveal melanoma cells but not in five lines with high ADA protein expression." (PMID 35804893, 2022).
uveal melanoma (continued). "As was seen with cells grown in soft agar, 80 and 160 μM of cordycepin strongly decreased monolayer colony formation in low ADA (92.1 and MM28) uveal melanoma cells but not in MP46 and Mel202 high ADA cells." (PMID 35804893, 2022). "Consistent with the role of Hsp90 in promoting HIF-1α and Akt stability, 80 μM and 160 μM cordycepin treatment significantly decreased protein levels of HIF-1α, Akt, ERK, and EGFR in ADA-low (92.1, MM28, Omm1) uveal melanoma cell lines, but not in those with high ADA (MP46 and MP38)." (PMID 35804893, 2022). "Indeed, in uveal melanoma cell lines with lower ADA expression or activity (92.1, MM28, and Omm1), 160 μM cordycepin treatment showed significant anticancer effects, while growth in multiple lines with high levels of ADA was not inhibited." (PMID 35804893, 2022).
varicella (1 paper, 2021). "Disseminated varicella caused by wild-type virus or following varicella vaccine in SCID patients, including ADA-SCID, have already been reported." (PMID 34502390, 2021).
viral hepatitis (1 paper, 2007). An acute or chronic inflammation of the liver parenchyma caused by viruses. "Also ADA was found to be increased in patients with viral hepatitis, and formation of ITP may result as a consequence of inosine accumulation." (PMID 19662223, 2007).